IL6 (interleukin 6)
Diseases named in the same sentence as IL6 in open-access papers (continued):
Sharing a sentence is not in itself a finding about the gene and the disease.
pancreatic cancer (continued). "All these results suggest that IL-6–mediated intracellular signaling cascades in tumor cells might play important roles in pancreatic cancer progression." (PMID 25609203, 2015). "Furthermore, pro-inflammatory markers, such as IL-6, IL-8, IL-10, and IL-1 receptor antagonist, are elevated in the serum of patients with pancreatic cancer, with IL-6 specifically being an indicator of poor prognosis." (PMID 26404380, 2015). "Here, we examined levels of typical serological factors, such as IL-6, TNF-α, and leptin, and used metabolomics to identify metabolites associated with cachexia in patients with pancreatic cancer and investigate intra-day variations in levels of these metabolites." (PMID 25411961, 2014). "Specifically CTL, NKT, γδT, NK, and IFNγ (Th1 type) cells were up-regulated, and Th17, PMN-MDSC, IL-6 and IL-8 (Th2 type) immune cells were inhibited, suggesting embelin can inhibit pancreatic cancer growth and inflammation by modulating tumor immune microenvironment." (PMID 24694877, 2014). "Indeed, there have been many studies describing the correlation between IL-6 elevation and poor prognosis in various types of cancers, including pancreas cancer." (PMID 23840274, 2013). "Combination of pretreatment YKL-40, IL-6, and CA 19.9 may have clinical value to identify pancreatic cancer patients with the poorest prognosis." (PMID 23840582, 2013). "Based on in vitro function studies, we confirmed that IL-6 could induce pancreatic cancer cell EMT and promote cell invasion." (PMID 23922983, 2013). "Therefore, our results indicated that over-production of the pro-inflammatory cytokine IL-6 promoted pancreatic cancer cell EMT." (PMID 23922983, 2013). "Similarly the production of IL-6 by Peripheral Blood Mononuclear Cells (PBMCs) in pancreatic cancer patients induced an acute phase protein response in another study." (PMID 21760776, 2011). "Furthermore, we demonstrated that IL-6 induced modest increases in cell proliferation only in pancreatic cancer cells (PL10) harbouring methylated SOCS-1 gene." (PMID 12865927, 2003). "Therefore, IL‐6 is a potential target for pancreatic cancer." (PMID 41583906, 2026). "Blocking IL-6 could not only slow tumor progression but also reactivate NK cells suppressed by peri-pancreatic adipose tissue or tumor-infiltrating cells, offering a promising therapeutic approach for the treatment of pancreatic tumors." (PMID 41008790, 2025). "Preclinical studies have demonstrated that treatment with anti-IL-6 or anti-IL-6R blocking antibodies can increase the efficacy of immunotherapy, reduce tumor progression, and increase T-cell infiltration in several murine tumor models, including those of pancreatic cancer." (PMID 39653766, 2025). "While the response to cytokines may vary between cell lines that may lack expression of their cognate receptors, the ubiquitous expression of gp130 in most pancreatic cancer cells allows for a response to a complex formed by IL-6 fused to its soluble receptor sIL-6R (IL-6-sIL-6R)." (PMID 40701148, 2025). "Additionally, pancreatic cancer-educated macrophages could protect cancer cells from complement-mediated cytotoxicity by up-regulating CD59 in an IL6/STAT3-dependent manner." (PMID 39518137, 2024). "In this study, we revealed that, of four human pancreatic cancer cell lines, GEM induced senescent features in PANC‐1 and AsPC‐1, leading to growth arrest, increased cell size, enhanced the expression of mRNAs encoding IL‐6/IL‐8 mRNA, and induction of β‐galactosidase." (PMID 38662379, 2024). "Of four pancreatic cancer cell lines (PANC‐1, AsPC‐1, CFPAC‐1, and PANC10.05), GEM induced senescent features in PANC‐1 and AsPC‐1 cells, including increases in the cell sizes and expression levels of mRNAs encoding interleukin (IL)‐6/IL‐8 and induction of β‐galactosidase." (PMID 38662379, 2024). "Also, IL-6 trans-signaling is constitutively active in several pancreatic cancer (PC) cell lines." (PMID 38715108, 2024).
pancreatic cancer (continued). "Additionally, elucidating the relationship between IL-6 and systemic inflammatory biomarkers may help characterize the features of pancreatic cancer that are commonly known to be unresponsive to immunotherapy, potentially leading to new therapeutic strategies." (PMID 38672257, 2024). "However, the relationship between baseline IL-6 levels in treatment-naïve patients with advanced pancreatic cancer and their subsequent prognosis, as well as the effectiveness of systemic chemotherapy and its connection with systemic inflammatory markers, remains largely unexplored." (PMID 38672257, 2024). "Considering IL-6’s pivotal role in driving tumorigenesis and metastasis, one might wonder whether inhibiting IL-6 could be a viable strategy in managing the progression of pancreatic cancer." (PMID 38828409, 2024). "In addition, patients with pancreatic cancer showed increased levels of plasma IL-6 protein." (PMID 38390872, 2024). "Interestingly, many of the pathways identified here are consistent with pathways identified in previous studies of NLRX1, including PI3K-AKT, MAPK, EGFR, NF-κB, and IL-6 signaling, and these pathways are all important to the initiation and progression of pancreatic cancer." (PMID 37342194, 2023). "Interestingly, analysis of 60 patients with advanced pancreatic cancer who received gemcitabine showed that the serum levels of IL1β and IL6 were poor prognostic factors for overall survival and the levels of these cytokines predicted the efficacy of gemcitabine in this population." (PMID 37772994, 2023). "The upregulation of IL6 44-46 and PD-L1 47 pathways could negatively impact anti-tumor immunity, providing the rationale for combining OV-mOX40L with neutralizing antibodies against IL6 or PD-L1 pathways for the treatment of pancreatic cancer." (PMID 37554264, 2023). "Similarly, coculture of mouse pancreatic tumor organoids with IL-6-expressing pancreatic stellate cells significantly enhanced cancer cell growth, whereas IL-6-deficient stellate cells failed to support extended tumor survival." (PMID 35267539, 2022). "Additionally, curcumin inhibits pancreatic cancer cell invasion through IL-6/ERK/NF-κB axis." (PMID 35630552, 2022). "For instance, in pancreatic cancer, two major types of CAFs could be distinguished, myofibroblast-like CAFs (myCAFs) and inflammatory CAFs (iCAFs), the latter being characterized by strong expression of IL-6." (PMID 36291767, 2022). "Therefore, it is reasonable to believe that IL-6 could also be a potential target for the prevention and adjuvant therapy of pancreatic cancer." (PMID 36105933, 2022). "Furthermore, individuals with pancreatic cancer who had their tumor resected had low specified pro-inflammatory cytokines (IL-6, IL-1, IFN-γ, and TNF-α), which were not linked to cancer cachexia." (PMID 35159388, 2022). "The upregulation of IL‐6/gp130 axis was evaluated using tumor‐derived IL‐6 level and intratumoral pSTAT3 expression in N‐inv of murine sciatic nerves by intraneural injection of Capan‐1 cell (N‐inv model) and using resected pancreatic cancer tissue and clinical data from 46 PDAC patients." (PMID 35578571, 2022). "Studies have shown that, in pancreatic cancer models, ω6-PUFAs have antitumor activity and inhibit the continuous growth of pancreatic tumors, ω6-PUFAs inhibits the proliferation of prostate cancer cells and regulates inflammatory IL-6 and TNF by affecting the production of cytokines-α." (PMID 35743814, 2022). "In addition, circRNA-100782 may regulate pancreatic cancer cell proliferation through interleukin 6 (IL-6) and signal transducer and activator of transcription 3 (STAT3) as a molecular sponge of microRNA-124." (PMID 34573523, 2021).
pancreatic cancer (continued). "However, high levels of IL-6, IL-10, and IL-8 in serum have been reported to negatively correlate with survival in pancreatic cancer patients, due to their role in stimulating inflammation and adverse changes in the tumor microenvironment that spurs the growth and development of pancreatic tumors." (PMID 34136405, 2021). "Moreover, IL-6 could facilitate the progression of pancreatic cancer, while specific inhibitor of IL-6 trans-signaling by the gp130Fc protein could depress tumor growth and further decreased the microvessel density, reduced the number of distant metastases." (PMID 34182543, 2021). "In addition, nsPEFs may inhibit the invasion of pancreatic cancer cells by downregulating IL-6 expression, although a detailed mechanism for this is yet to be elucidated." (PMID 33634030, 2020). "Therefore, the IL-6 signaling pathway may serve as a promising therapeutic target for pancreatic cancer." (PMID 33634030, 2020). "Blocking IL-6 may not only inhibit tumor growth but also it may rescue NK cells from suppression mediated by the adipose tissue or tumor tissues and offer an attractive and effective therapeutic strategy to target pancreatic tumors." (PMID 29977235, 2018). "This suggests that IL-6 could be a useful prognostic biomarker for patients with pancreatic cancer." (PMID 30038723, 2018). "Increased IL-6 secretion in the presence of decreased IFN-γ secretion induced by surrounding or infiltrating adipose tissue within tumor microenvironment may constitute a significant driving force in the expansion of pancreatic tumors." (PMID 29977235, 2018). "In addition to the inflammatory response, IL-6 is associated with numerous tumor cell biological behaviors, including growth, survival, metastasis, angiogenesis, EMT, and chemoresistance, which plays a role in the promotion of pancreatic cancer development." (PMID 29254283, 2017). "In vitro and in vivo experiments confirmed that IL-6 could inhibit apoptosis of pancreatic intraepithelial neoplasia (PanIN) cell lines and promote the development of precancerous lesions and pancreatic cancer, which indicated that IL-6 is involved in early stages of pancreatic cancer development." (PMID 25609203, 2015). "In pancreatic cancer models, BET inhibition reduces HO-1 expression in macrophages and suppresses tumor-promoting cytokines such as IL-6, CCL2, and GM-CSF, demonstrating a direct link between BET activity and the immunosuppressive tumor microenvironment." (PMID 41583469, 2025). "In the pancreatic cancer TME, sialic acid modulates monocytes to secrete IL-10 and IL-6, which subsequently activate the SIGLEC9 receptor, promoting the polarization and differentiation of monocytes into immunosuppressive TAMs." (PMID 41418390, 2025). "IFIT3 specifically promotes pancreatic cancer cell metastasis by inhibiting IFIT2’s pro-apoptotic effects and upregulating vascular endothelial growth factor (VEGF) and interleukin-6 (IL-6) secretion." (PMID 40061935, 2025). "When PDAC interact with NK cells, IL-6 secretion increases, while IFN-γ secretion decreases, potentially encouraging pancreatic tumor growth." (PMID 41008790, 2025). "Cancer stem cells (CSCs) hijack stromal signaling to evade immunity and support metastasis, particularly in breast and pancreatic cancers, where CSC–fibroblast crosstalk via IL-6 and FAP plays a critical role." (PMID 40643502, 2025). "LIF is an important component of the IL‐6 cytokine family; studies have shown that the expression level of LIF in pancreatic cancer tissue is significantly increased compared with normal pancreatic tissue, and CAFs are the main cell source of LIF." (PMID 40751418, 2025). "Dosch et al36 demonstrated that the human IL-1R1 antagonist anakinra significantly reduced IL-6 levels and inhibited STAT3 activation in pancreatic tumors derived from PKT mice." (PMID 40060615, 2025).
pancreatic cancer (continued). "The IL-6/JAK2/STAT3 signaling pathway is vividly involved in the pancreatic intraepithelial neoplasia (PanIN) and the development of pancreatic cancer." (PMID 39201692, 2024). "There is an inverse relationship between miR-34a and IL6 levels in various cancers, leading to increased expression of IL6R mRNA and IL6/STAT3 signaling, as observed in OC, colorectal, and pancreatic cancer." (PMID 39766086, 2024). "Studies have shown that the inhibition of IL-6/STAT3 signaling pathway reduces EMT and inflammation in pancreatic cancer cells." (PMID 39195299, 2024). "We detected the changes in cytokine secretion in pancreatic cancer cells after TIM‐4 overexpression, the results demonstrated a notable reduction in IL‐6, hindering Treg differentiation." (PMID 39235042, 2024). "IL-6 activated STAT3 and increased its phosphorylation, thus upregulating matrix metalloproteinase 2 and vascular endothelial growth factor in the pancreatic cancer line Capan-2." (PMID 38273295, 2024). "Murine pancreatic cancer cells (KPC) were orthotopically implanted into the pancreas of wild‐type, IL‐6−/−, and hepatocyte STAT3−/− male and female mice." (PMID 38632714, 2024). "In pancreatic cancer, a positive correlation has been observed between high PTX3 expression and inflammatory markers, including serum CRP and IL-6 levels." (PMID 39594709, 2024). "Another study on pancreatic cancer showed that α-SMA+ CAF cells produce macrophage colony-stimulating factor 1 (M-CSF-1), IL-6, TGF-β, and CCL2 to promote monocyte recruitment and macrophage polarization into M2 macrophages." (PMID 39030445, 2024). "During PDAC, quiescent pancreatic stellate cells are activated and transformed into the myofibroblast-like phenotype and secrete molecules like TGFβ, IL-6, SDF-1, HGF and galectin-1, involved in pancreatic cancer progression." (PMID 39195299, 2024). "To sum up, we discover that BA inhibits the expression of IL-6 and phosphorylation of AKT/STAT3 by mediating changes in miR-365/BTG2, thereby inhibiting the progression of pancreatic cancer." (PMID 37415745, 2023). "For instance, the fibroblasts-derived CSF-1, IL-6 and CCL2 has been found to promote macrophages infiltration and M2 phenotype polarization process in pancreas cancer." (PMID 37325617, 2023). "In pancreatic cancer, IGF-IR, STAT3, HIF-1α, IL-6, IGF-1, amongst others, have been described to be active and linked to the HSP90 pathways." (PMID 36966394, 2023). "Of the five most used proteins in the BTC signatures (IL-6, IL-15, PTN, CCL23, and MUC-16), only IL-6 was used in the primary pancreatic cancer signatures." (PMID 36831406, 2023). "Together, our findings suggest that combined blockade of IL-6 and CTLA-4 can regress pancreatic tumors via a potentially unique mechanism by imparting CD4+ and CD8+ T cell–mediated antitumor immunity." (PMID 36881480, 2023). "We observed that SC144 suppresses both IL-6 and OSM signaling in a dose-dependent manner in human L3.6pl pancreatic cancer cells." (PMID 36495330, 2023). "Thus, targeting IL-6 may be a promising treatment option for pancreatic cancer." (PMID 37415745, 2023). "In a murine model of pancreatic cancer, GLI-1 binds to the IL-6 promoter and increase its expression, leading to a more aggressive phenotype." (PMID 38188300, 2023). "Robinin (1 μM/ml) largely attenuated IL-6 and TNF-α expression in Mia-PACA2 and PANC-1, which certified that Robinin can obviously inhibit the inflammation in pancreatic cancer." (PMID 38110966, 2023). "Several downstream proteins have been discussed to be tumor regulator in pancreatic cancer, such as FBXO11, IL-6 and RBM3 except SLC38A2." (PMID 37005877, 2023). "IL6 derived from CAFs inhibits natural killer cell activity and activates STAT3 in pancreatic cancer cells." (PMID 36010986, 2022). "PF inhibits the proliferation of pancreatic cancer cells by interfering with the MAKP signaling pathway, IL-10, IL-6, and additional inflammatory factors." (PMID 36339551, 2022).
pancreatic cancer (continued). "Mechanistically, circCUL2 functioned as a ceRNA and modulated the miR-203a-3p/MyD88/NF-κB/IL6 axis, thereby further activating the STAT3 signaling pathway in pancreatic cancer cells to induce the progression of PDAC." (PMID 35189958, 2022). "In particular, the addition of ablation to CP4 immunotherapy significantly increased IL-6, Adgre1, Cd64, Ly6a2 and Ly6c2 in the MT4 pancreatic tumors, indicating a population of monocytes and macrophages was particularly enhanced by this combination treatment." (PMID 36451859, 2022). "Schwann cells activated by pancreatic cancer cells released IL6, which activated STAT3 signaling and induced the EMT process in pancreatic cancer cells, thereby promoting the metastasis of pancreatic cancer cells." (PMID 36522730, 2022). "circCUL2 functioned as a ceRNA and modulated the miR-203a-3p/MyD88/NF-κb/IL6 axis, inducing the conversion of NFs into iCAFs, thereby further activating the STAT3 signaling pathway in pancreatic cancer cells to induce the progression of PDAC." (PMID 35189958, 2022). "circCUL2- induced iCAFs contributed to the tumorigenesis and metastasis of PDAC through increased secretion of IL6 and further activation of the STAT3 signaling pathway in pancreatic cancer cells." (PMID 35189958, 2022). "Nab‐paclitaxel can block pancreatic cancer cell migration and invasion effects by increasing CXCL10 expression in cancer cells and inhibiting IL-6 expression in CAF cells." (PMID 35468838, 2022). "Taken together, these clinical trials shed light on the importance of IL6, TGFβ, CXCR4, and CD40 in cancer treatment, as well as their potential therapeutic effects on pancreatic cancer." (PMID 35453676, 2022). "Moreover, after vaccination, IL-6 expression was lower in patients with good response compared to patients with poor response, which was in line with a published study concluding that the elevation of IL-6 correlated with poor survival in pancreatic cancer patients." (PMID 36248865, 2022). "Although the benefits of targeting IL6, TGFβ, CXCR4, and CD40 in pancreatic cancer remain elusive, clinical trials for these factors in other cancer types have shown promise." (PMID 35453676, 2022). "The CAC-associated pro-inflammatory cytokines, TNF-α and IL-6 and CCM from PANC-1 human pancreatic cancer cells promoted lipolysis in mature 3T3-L1 adipocytes as judged by an increase in glycerol release and free fatty acids (FFA)." (PMID 35684106, 2022). "Mechanistically, circCUL2 functioned as a ceRNA and modulated the miR-203a-3p/MyD88/NF-κB/IL6 axis, thereby further activating the STAT3 signaling pathway in pancreatic cancer cells to induce PDAC progression." (PMID 35189958, 2022). "IL-6 from CAFs inhibits NK cell activity, and activates signal transducer and activator of transcription 3 (STAT3) in pancreatic cancer cells." (PMID 33572223, 2021). "EVs from solid tumours such as breast and pancreatic cancer have been previously shown to increase the secretion of several pro-inflammatory factors including MMP9 and IL-6 from THP-1 monocytic cells." (PMID 33984826, 2021). "There are drugs used in pancreatic cancer-induced cachexia that inhibit cytokines such as e.g., TGF-β, TNF-α and IL-6." (PMID 33557173, 2021). "IL-6 activated the JAK2/STAT3 pathway, which accelerated cell cycle progression by promoting CyclinD1 expression in pancreatic cancer." (PMID 34165442, 2021). "In the presence of isolated effector CD4+ T cells, pancreatic cancer cells show upregulation of VIM, L1CAM and ZEB1, combined with a more migratory phenotype, which was reverted by blocking IL6 and TNFα." (PMID 34459003, 2021).